C3 (complement C3)
Diseases named in the same sentence as C3 in open-access papers (continued):
Sharing a sentence is not in itself a finding about the gene and the disease.
hemolysis (7 papers, 2020 to 2025). Disruption of the integrity of the erythrocyte membrane causing release of hemoglobin. "In this setting, heterozygous C3 variants that impair pegcetacoplan binding could make the PNH patient exceptionally susceptible to intravascular hemolysis crises, particularly during acute-phase responses or infections that transiently increase C3 synthesis." (PMID 41383613, 2025). "In PNH a C5b-9-dependent pathway leads to membrane-attack-complex-mediated intravascular hemolysis, and a C3-dependent pathway results in deposition of the opsonin C3dg on the erythrocyte, explaining ongoing extravascular hemolysis in patients treated with eculizumab." (PMID 32447506, 2020).
hyperuricemia (7 papers, 2018 to 2024). An abnormally high level of uric acid. "Hyperuricemia and C3 deposition were independent risk factors for IgAN, as were the Oxford T-score and a declining eGFR." (PMID 33925441, 2021).
immune complex disease (7 papers, 2013 to 2025). "Even though SLE is an immune complexes disease, its association with homozygous C3 deficiency has only been reported in 3 Japanese patients, and so far, partial deficiencies of complement proteins have not been associated with SLE." (PMID 25886501, 2015). "Lowered C3 concentrations are classically found in patients with immune complex diseases, such as systematic lupus erythematosus, which in turn can mimic psychoses." (PMID 32937787, 2020). "HSP has also been regarded as an immune complex disease; however, hypocomplementemia with low serum or plasma C3 and/or C4 levels was not commonly shown and usually transient in patients with acute HSP." (PMID 25760949, 2015). "The plasma levels of C1q, C3, and C4, which are an indirect and insensitive mirror of complement activation and immune complex disease, were not correlated to any of the FXIIa-AT or FXIIa-C1INH complexes." (PMID 24299152, 2013).
interstitial lung disease (7 papers, 2017 to 2024). A diverse group of lung diseases that affect the lung parenchyma. "Strong immunoglobulin and C3 expression in the lungs involve lung injury related to dermatomyositis-related interstitial lung disease." (PMID 36934274, 2023). "However, patients with dermatomyositis-related interstitial lung disease showed significantly stronger expression of C3 (p < 0.001), IgG (p < 0.001), and IgM (p = 0.001) in the lungs than control." (PMID 36934274, 2023). "Moreover, lung C3, but IgG, IgA, nor IgM expression was significantly stronger in MDA5 autoantibody-positive dermatomyositis-related interstitial lung disease (n = 9) than in MDA5 autoantibody-negative dermatomyositis-related interstitial lung disease (n = 9; p = 0.022)." (PMID 36934274, 2023).
leukocytosis (7 papers, 2012 to 2025). "Venous air embolism triggered thromboinflammation in vivo in pigs, reflected by increased plasma complement C3 activation, leukocytosis, and coagulation." (PMID 35371063, 2022). "Also, this group presented leukocytosis (p= 0.044), neutrophilia (p = 0.003), higher CK levels (p = 0.005), and had C3 (p = 0.07) and C4 (p = 0.046) hypocomplementemia in comparison to DM patients without TMA." (PMID 41516191, 2025).
lupus erythematosus (7 papers, 2012 to 2025). An autoimmune, connective tissue chronic inflammatory disorder affecting the skin, joints, kidneys, lungs, heart, and the peripheral blood cells. "Complement C3 and C4 deposition increased on autoantibody targets in spite of the decreased serum complement concentrations, and decreased on other autoantigens, demonstrating the imbalance of complement function in patients with lupus erythematosus." (PMID 22984570, 2012). "Patients with active lupus erythematosus may have lower levels of C3 and C4 than healthy controls." (PMID 28938643, 2017).
Lymphadenopathy (7 papers, 2012 to 2025). Enlargement (swelling) of a lymph node. "Patients with severe systemic disease (including lymphadenopathy, central nervous system, peripheral nervous system, pulmonary, renal, cutaneous, articular, hematological, and muscular damage) had a higher frequency of RF and low C3 and C4 levels." (PMID 38633257, 2024).
lymphoma (7 papers, 1978 to 2025). A malignant (clonal) proliferation of B- lymphocytes or T- lymphocytes which involves the lymph nodes, bone marrow and/or extranodal sites. "Although the mechanisms underlying lymphoma pathogenesis in patients with pSS have not been well identified, low C3/C4 levels may help improve the survival of autoreactive B-cells in such patients and further, through mutations, increase the risk of lymphoid malignancy occurrence." (PMID 35348930, 2022). "Importantly, C3 depletion by cobra venum factor, or the related drug (HC3-1496), appears to effectively overcome this mechanism and improve the activity of rituximab in lymphoma-bearing mice." (PMID 21437222, 2010).
meningitis (7 papers, 2006 to 2024). A disorder characterized by acute inflammation of the meninges of the brain and/or spinal cord. "In a mouse model of meningitis induced by Streptococcus pneumonia infection, C1q and C3 deficiency led to reduced cerebrospinal fluid (CSF) leukocyte counts in comparison with infected wild-type (WT) mice." (PMID 26822321, 2016). "Additionally, complement C1q and C3 are critical for the innate immune response to Streptococcus pneumoniae in the CNS, and C3−/− mice were shown to display reduced expression of IL-1β, IL-12 and MIP-1γ in the CNS in a meningitis animal model." (PMID 26822321, 2016).
myasthenia gravis (7 papers, 2018 to 2026). Myasthenia gravis (MG) is a rare, clinically heterogeneous, autoimmune disorder of the neuromuscular junction characterized by fatigable weakness of voluntary muscles. "Furthermore, C3 complement deposits are also present in the neuromuscular junction of patients with myasthenia gravis, and exacerbation of myasthenia gravis is accompanied by increased complement consumption." (PMID 39087011, 2024).
Oral ulcer (7 papers, 2013 to 2025). Erosion of the mucous mebrane of the mouth with local excavation of the surface, resulting from the sloughing of inflammatory necrotic tissue. "SLE patients presenting as MAS had significantly higher SLEDAI-2K scores, lower complement C3 and C4 levels, and a higher frequency of oral ulcers and serositis compared to those who developed MAS during the established course of SLE." (PMID 40508215, 2025). "Patients with MAS as an initial manifestation of SLE also demonstrated lower C3 levels, lower C4 levels, and a higher proportion of oral ulcers and serositis compared with patients with MAS that occurred during the course of lupus." (PMID 39110110, 2024). "However, in SLE patients with joint pain, butterfly rash and oral ulcer, complement C3 and C4 levels were markedly reduced (P<0.05)." (PMID 24223657, 2013). "A higher risk of joint pain, butterfly rash and oral ulcer in SLE patients was demonstrated along with the reduction of complement C3, but not C4 (P<0.05)." (PMID 24223657, 2013). "This suggests that when joint pain, butterfly rash and oral ulcer appear, patients with reductions in complement C3 and C4 levels and unchanged CRP levels may be diagnosed with SLE." (PMID 24223657, 2013). "In a previous study, complement C3 and C4 levels were observed to be reduced in SLE patients with joint pain, butterfly rash and oral ulcers." (PMID 24223657, 2013).
periodontal disease (7 papers, 2017 to 2024). "Deletion of C3 rescued the periodontal inflammation phenotype in diabetic mice, suggesting that the control of C3 levels in diabetic patients may reduce the risk of periodontal disease at an early stage." (PMID 32794619, 2020). "Another study identified C3 as one of the top 21 most promising candidate genes involved in periodontal disease using microarray experiments." (PMID 35571048, 2022). "To further prove that C3 is a key molecule for T2DM to promote periodontal disease, we established a C3 knockout mouse model and induced them with T2DM." (PMID 32794619, 2020). "Another study has used integrative gene prioritization and databases from genome-wide association studies and microarray experiments, and identified C3 among the top 21 most promising candidate genes involved in periodontal disease." (PMID 30915073, 2019). "Based on the results from a C3-knock-out mouse model, C3-targeted drug candidates have been suggested as novel immunotherapeutics for periodontal disease." (PMID 31749804, 2019). "The complement factors C3 and C5 were previously identified as key players in periodontal disease." (PMID 33803323, 2021). "Notably, considerable research has focused on complement C3 inhibition in periodontal diseases." (PMID 39439802, 2024). "The importance of C3 in periodontal disease pathogenesis was definitively confirmed in non-human primates locally treated with a potent C3 inhibitor, the compstatin analog Cp40 (AMY-101)." (PMID 28748042, 2017).
peritonitis (7 papers, 2008 to 2023). Inflammation of the peritoneum (tissue that lines the abdominal wall and covers most of the organs in the abdomen). "For instance, although the possible function of ADAMTS5 on C3 is unknown, the ability of leukocyte elastase to process complement is known since the late 1970s, whereas a more recent study found that MMP12 was able to process and inactivate C3 in murine peritonitis." (PMID 32917786, 2020). "The MBL-A KO mouse has been examined in the cecal ligation and puncture (CLP) model of acute septic peritonitis and interestingly it was revealed that MBL-A KO mice showed increased survival compared to WT mice and to C3 KO mice." (PMID 28634324, 2017). "We measured levels of sC5b-9, C3 and C4 in PDF on days 1, 2 and 5 post-onset of peritonitis in 104 episodes of infectious peritonitis in PD patients from 2008 and retrospectively compared levels with clinical outcomes." (PMID 28046064, 2017). "Serum levels of C3, C4 and CH50 were not related to prognosis of peritonitis." (PMID 28046064, 2017).
psychosis (7 papers, 2019 to 2023). "In the few studies on the complement levels of patients with psychosis, most of the results focused on complement C3 and C4, while there are few studies on the role of complement C5 in psychosis, and most of them are insignificant findings." (PMID 36631451, 2023). "One included study compared C1q, C3 and C4 levels in healthy controls with three groups of cases: patients with chronic schizophrenia, patients with FEP and individuals at clinical high-risk (CHR) for psychosis." (PMID 32456884, 2020).
renal dysfunction (7 papers, 2016 to 2025). "Our study is the first to explore the correlation between the expression of complement C3a/C3aR, C5a/C5aR and prognosis in IgAN patients with severe renal dysfunction." (PMID 38951265, 2024). "Therefore, our aim was to assess the biomarkers helpful for the diagnosis of early renal dysfunction by testing for cryoglobulins, RF, complement C3, cystatin C, and creatinine/cystatin C ratio in newly diagnosed HCV-infected patients." (PMID 36466932, 2022). "To assess this possibility we contrasted the receiver operating characteristics (ROC) for the five analytes with the highest fold-difference between ALN and ANLN, with previously proposed urinary and serum (C3, anti-dsDNA) biomarkers, as well as established markers of renal dysfunction." (PMID 27716443, 2016).
SARS-CoV infection (7 papers, 2018 to 2024). "A previous study reported that activation of complement component C3 exacerbates disease in ARDS due to SARS-CoV infection, suggesting that C3 inhibition may also alleviate the inflammatory lung complications of such infection." (PMID 38178176, 2024). "Together, although C3–/– mice produced a robust immune cell infiltration following SARS-CoV infection, they had significant reductions in both inflammatory monocytes and neutrophils relative to controls; both cell types that are associated with SARS-CoV pathogenesis." (PMID 30301856, 2018). "Also in murine models it has been previously shown that, during infection with different human coronaviruses, depletion or blockage of complement component 3 (C3) in SARS-CoV infection and complement component 5 (C5) in MERS-CoV infection resulted in milder disease severity." (PMID 34194438, 2021). "C3 was an important host mediator of SARS-CoV-induced disease and it regulates a systemic proinflammatory response to SARS-CoV infection." (PMID 32746940, 2020). "While work by other laboratories has shown that C3-deficient mice are extremely susceptible to both H5N1 and H1N1 influenza virus infection, the role of complement in SARS-CoV infection has not yet been evaluated in vivo." (PMID 30301856, 2018).
status epilepticus (7 papers, 2022 to 2025). Status epilepticus is defined as a continuous seizure lasting more than 30 min, or two or more seizures without full recovery of consciousness between any of them. "C1q and C3, initiators of the classical pathway, localize to epileptic human cortex and increase after status epilepticus in models, correlating with synaptic loss and gliosis." (PMID 41458814, 2025). "Global genetic C3 knockout prevents status epilepticus (SE)–induced hippocampal neuronal loss and recognition memory deficits, supporting a causal role of C3 in seizure-related neurodegeneration." (PMID 41346378, 2025). "In the current study, we investigated the role of complement C3 in memory loss induced by prolonged and continuous seizure activity, also known as status epilepticus (SE)." (PMID 38035266, 2023). "Increased C1q (and downstream C3) has been documented in resected human TLE cortex and after status epilepticus in rodents, in association with dendritic/synaptic pathology." (PMID 41458814, 2025). "C1q-C3 signaling activation in status epilepticus correlates with epileptic seizure frequency, and blocking C3 signaling reduces seizure activity and neuronal injury." (PMID 35625943, 2022). "C3/C3aR signaling strengthens microglia-astrocyte communication, promotes gliosis, and exacerbates neuronal injury; genetic deletion or pharmacologic depletion of C3 mitigates status-epilepticus-related neurodegeneration and memory deficits in models, highlighting this axis as a tractable target." (PMID 41458814, 2025). "RNA sequencing revealed upregulation of C3 in reactive GLAST+ astrocytes from laparotomy, and increased levels were also noted in astrocytes from both a pilocarpine-induced status epilepticus model, and traumatic brain injury brain." (PMID 40294039, 2025).
systemic sclerosis (7 papers, 2013 to 2025). A chronic disorder, possibly autoimmune, marked by excessive production of collagen which results in hardening and thickening of body tissues. "Autoantibodies to systemic sclerosis and antinuclear antibodies (ANA’s) were negative, with no complement consumption (C3: 119mg/dL and C4: 19 mg/dL; reference range: C3, 90-180 mg/dL and C4, 12 - 36 mg/dL)." (PMID 39963651, 2025).
tuberculosis (7 papers, 2012 to 2025). A chronic, recurrent infection caused by the bacterium Mycobacterium tuberculosis. "The study of host-pathogen interactions identified biomarkers of resistance/susceptibility to tuberculosis in wild boar such as complement component 3 (C3) and methylmalonyl coenzyme A mutase (MUT) that were used for vaccine development." (PMID 22848869, 2012). "Furthermore, the downregulation of Tnf, Mapk11, C3, Il1a, and Il1b in the tuberculosis and pertussis pathways reduces macrophages' ability to opsonize bacteria, perform phagocytosis, and initiate inflammatory responses." (PMID 40206211, 2025). "In addition, the up-regulation of C3 in the lymph nodes and tonsils has been correlated with tuberculosis resistance in wild boar." (PMID 27820836, 2016). "Decreased C3 activation by the mutant strain as observed in the present investigation further stresses the significance of devR gene in the inflammation and pathogenesis of tuberculosis." (PMID 26904726, 2013).
uveitis (7 papers, 2017 to 2025). An inflammatory process affecting a part of or the entire uvea. "Given the well-established genetic profile of complement genes in uveitis, significant linkage evidence points to the C3 locus, which encoded a “central” factor of the cascade." (PMID 28408754, 2017). "This study aimed to provide additional insights into this interest by testing the “central” factor of the complement system, C3 gene variants, in two uveitis entities." (PMID 28408754, 2017). "Cluster 3 (C3) represented a gene signature associated with uveitis that includes core B cell genes, including the MS4A1 gene (encoding CD20), Toll-Like Receptors (TLR) TLR7 and CD180 that regulates B cells responses, and ITSN2 a key gene required for antibody formation in B cells." (PMID 33042130, 2020). "Together with our previous studies and others, we herein aimed to explore whether C3 gene variants are involved in the genetic predisposition to uveitis." (PMID 28408754, 2017). "Clinical validation already exists (e.g., anti-VEGF for leak/ischemia; C3 inhibition for GA; adalimumab for refractory uveitis)." (PMID 41394857, 2025). "Based on the crucial role innate immune mediator C3 plays in EAAU and EAU models, we explored the potential association of the C3 gene with uveitis." (PMID 28408754, 2017). "The non-significant results identified in this study suggest that the C3 gene may confer either no or limited risk for uveitis susceptibility, whether in AU or NIPU patients." (PMID 28408754, 2017). "However, a higher expression of C3 and CFH proteins was observed in the aqueous humor, indicating that the inflammation seen in uveitis is a localized change in the anterior chamber of the eye and cannot be seen in the blood unless there is a blood-retinal barrier breakdown." (PMID 38187376, 2023). "The expression of C3 and CFH genes was significantly downregulated in the patients with non-infectious uveitis as compared to controls (C3, AAU vs. controls, FC -5.0 ± 0.7; *p = 0.03; CFH AAU vs. controls, FC -6.67 ± 1.0; *p = 0.04)." (PMID 38187376, 2023).
antiphospholipid syndrome (6 papers, 2017 to 2025). A disorder caused by the presence of autoantibodies directed against phospholipids, causing a hypercoaguable state, which may result in blood clots, stroke, heart attack, and in women, significant pregnancy-related complications, including miscarriage and still birth. "Studies assessing the correlation of C3 and C4 serum levels with obstetric outcome in pregnant women with anti-phospholipid syndrome." (PMID 32973817, 2020).
bladder cancer (6 papers, 2020 to 2023). "Studies have demonstrated altered expression of C3 in bladder cancer patients, indicating its potential diagnostic and prognostic significance." (PMID 38201450, 2023). "Other studies have also implicated C3 in the context of bladder cancer, highlighting its association with immune-related processes and potential clinical implications." (PMID 38201450, 2023). "Upon activation, C3 is cleaved and deposited on pathogenic cells, which means that an active infection or pathogenic condition is expected to reduce C3 levels in the blood as shown for bladder cancer patients." (PMID 36004048, 2022). "The expression of complement C3 (C3) in the sEV fractions of bladder cancer patients was increased in this biomarker discovery study." (PMID 37371512, 2023). "This opposite behavior of aptamers binding C3–CH and CH only is consistent with a report that found higher levels of complement factor H in urine of bladder cancer patients." (PMID 36004048, 2022).